PPARD (peroxisome proliferator activated receptor delta)
Diseases named in the same sentence as PPARD in open-access papers (continued):
Sharing a sentence is not in itself a finding about the gene and the disease.
cardiac hypertrophy (34 papers, 2009 to 2025). "Mice deficient in PPARδ have been found to have cardiac dysfunction, myocardial hypertrophy, and heart failure, evidence that PPARδ plays a role in myocardial pathology." (PMID 37551283, 2022). "By contrast, inducible and conditional vascular-specific overexpression of PPARδ was reported to rapidly cause cardiac hypertrophy." (PMID 30620754, 2019). "PPARδ deficiency in the heart leads to cardiac dysfunction, myocardial lipid accumulation, cardiac hypertrophy/remodeling and heart failure." (PMID 31032335, 2018). "Among PPARs, PPARδ is widely observed in diabetic disorders, likely because cardiomyocyte-restricted PPARδ deletion causes cardiac hypertrophy." (PMID 27519769, 2016). "Inducible cardiomyocyte PPARδ−/− results in cardiac dysfunction associated with oxidative damage and mitochondrial abnormalities and cardiac hypertrophy." (PMID 26713088, 2015). "Since Ang II has been implicated in cardiac hypertrophy, we assessed whether activation of PPARδ might affect cell surface area (CSA) in H9c2 cells exposed to Ang II." (PMID 34439471, 2021). "Thus, the present work aimed to examine the effect of PPARδ activation on catalase expression to determine whether there is a mechanistic link between vasoactive peptide Ang II-associated cardiac hypertrophy and PPARδ-mediated upregulation of catalase." (PMID 34439471, 2021). "miR-29a amelioration of myocardial hypertrophy is explained through its effect on the nuclear receptor peroxisome proliferator-activated receptor delta (PPARD) and through downregulation of the atrial natriuretic factor." (PMID 41008658, 2025). "Through the regulation of peroxisome proliferator-activated receptor delta (PPARδ), miR-29a was said to reduce cardiac hypertrophy." (PMID 37035745, 2023). "Mice deficient in peroxisome proliferator-activated receptor delta (PPARδ) can have cardiac dysfunction, myocardial hypertrophy, and heart failure." (PMID 37551283, 2022). "We identified catalase as an effector molecule in the PPARδ-mediated reduction of ROS accumulation, thereby preventing cardiac hypertrophy induced by Ang II." (PMID 34439471, 2021). "The impact of PPARδ activation has also been evaluated in relation to AngII-induced cardiac hypertrophy, revealing an ameliorating effect of the agonist GW0742 in neonatal rat cardiomyocytes." (PMID 34360540, 2021). "Accordingly, the present findings suggest a primary role for PPARδ as a new potential therapeutic target to alleviate cardiac hypertrophy." (PMID 34439471, 2021). "It has also been demonstrated that PPARδ activation inhibits cardiac hypertrophy induced by Ang II and hyperglycemia through suppression of the intracellular Ca2+ signaling pathway and free radical production in cultured H9c2 cardiomyocytes." (PMID 34439471, 2021). "Pharmacological studies show that baicalin and Moringa oleifera Seeds, both extracted from plants, protect the heart from TAC-induced pressure overload or hypertension from the development of hypertrophy via enhancing cardiac PPARδ expression." (PMID 31032335, 2018). "The same group went on to demonstrate that mice with induced vascular-specific overexpression of PPARδ show rapid cardiac hypertrophy." (PMID 31032335, 2018). "Under various cardiac hypertrophy conditions, most studies show cardiac PPARδ is decreased as those of PPARα." (PMID 31032335, 2018). "In the present study, we used L-165,041 to activate PPARδ and investigated whether this reduced myocardial hypertrophy." (PMID 37551283, 2022). "Based on its ability to protect the cardiovasculature, investigating the potential mechanisms of PPARδ in the development of cardiac hypertrophy could prove fruitful from a therapeutic perspective." (PMID 34439471, 2021). "PPARδ activation improves angiotensin II-induced cardiac hypertrophy in vitro." (PMID 31032335, 2018).
cardiac hypertrophy (continued). "Indeed, mice with cardiac-specific deletion of PPARD develop age-dependent cardiac lipotoxicity, cardiac hypertrophy, end-stage dilated cardiomyopathy, and decreased survival." (PMID 23372767, 2013). "More importantly, treatment with irbesartan remarkably attenuated ACE2-dificiency induced myocardial hypertrophy and ultrastructure injury along with augmentation of cardiac PPARγ level, without having a differential effect on the expression of PPARα and PPARδ." (PMID 24067190, 2013). "However, it remains unclear whether PPARδ can prevent cardiac hypertrophy simply by reducing ROS accumulation." (PMID 34439471, 2021). "Cardiomyocyte-specific deletion of PPARδ (CM-PPARδ) results in a downregulation of key FAO genes that limits the myocardial lipid-consumption rate, leading to triacylglyceride accumulation, cardiac hypertrophy, congestive HF, and reduced survival." (PMID 34360540, 2021). "In fact, multiple studies have demonstrated that pharmacological activation of PPARδ by specific ligands can improve cardiac hypertrophy in cellular and animal models through mechanisms not yet fully elucidated." (PMID 34439471, 2021).
Hepatic steatosis (27 papers, 2012 to 2025). Steatosis is a term used to denote lipid accumulation within hepatocytes. "Mice conditionally expressing human PPARδ demonstrated pronounced weight loss and promoted hepatic steatosis when treated with GW501516 (PPARδ-agonist) when compared to wild type mice." (PMID 26604919, 2015). "We demonstrate that autophagy is associated with PPARδ-induced hepatic fat clearance in vivo by using two rodent models, the db/db mouse and the high fat diet-fed mouse, which have been shown previously to mimic human hepatic steatosis." (PMID 30814493, 2019). "In summary, we show that liver specific expression of human PPARδ in mouse liver promoted hepatic steatosis that was associated with significant loss of fat mass, suggesting extensive adipose tissue lipolysis and consequently an influx of fatty acids into the liver." (PMID 26604919, 2015). "The selective PPARD agonist, seladelpar, ameliorated hepatic steatosis in diabetic obese mice via an autophagy-mediated pathway, and also inhibited lipotoxicity and improved NASH." (PMID 39899669, 2025). "In this study, we have shown that PPARδ overexpression or agonist induction prevents hepatic steatosis in obese mice." (PMID 30814493, 2019). "In summary, we have demonstrated that PPARδ has a beneficial effect in attenuating hepatic steatosis by activating autophagy in vivo and in vitro." (PMID 30814493, 2019). "In long term, the activation of PPARδ by GW501516 turned out to be protective against liver steatosis." (PMID 26604919, 2015). "For example, adenovirus-mediated overexpression of PPARδ was enough to ameliorate hepatic steatosis in obese db/db mice in 7 days." (PMID 26604919, 2015). "Our results show that both PPARδ and PPARα receptors are essential for GW501516-driven adipose tissue reduction and subsequently hepatic steatosis, with PPARα working downstream of PPARδ." (PMID 26604919, 2015). "Similar to our findings, Zengpeng and colleagues demonstrated that dietary genistein supplementation resulted in the upregulation of gene transcription associated with fatty acid beta-oxidation, including PPARα, PPARδ, ACOT8, ACAD8, and ACADs in the liver of laying hens induced fatty liver." (PMID 38540097, 2024). "A previous in vivo study demonstrated that the activation of NF-ĸB signaling pathway and the reduction of PPARδ expression played essential roles in NAFLD induced via testosterone deficiency and HFD in pigs, and hepatic steatosis and inflammation were alleviated after testosterone treatment." (PMID 38540097, 2024). "PPARδ further reduced the expression of PTEN to enhance insulin sensitivity in hepatic steatosis." (PMID 34140896, 2021). "Furthermore, H&E-stained liver sections showed that hepatic steatosis was greatly improved, and PPARδ overexpression significantly decreased hepatic TG levels in a quantitative assay." (PMID 30814493, 2019). "In accordance with the beneficial effects of PPARδ in improving hepatic steatosis, PPARδ could also protect against liver inflammation and fibrosis." (PMID 30814493, 2019). "Hitherto, the role of PPARδ in liver steatosis remained an open question." (PMID 26604919, 2015). "Increase expression of PPARD has been reported in hepatic steatosis that is induced by oleic acid." (PMID 24993133, 2014). "So far, role of PPARδ in promoting or preventing hepatic steatosis is an open question." (PMID 22550474, 2012). "Notably, PPARδ target genes were also found to be implicated in multiple human phenotypes that are highly reminiscent of FAO disorders, including, but not limited to, hypoglycemia, hepatic steatosis, and rhabdomyolysis." (PMID 36078043, 2022). "Moreover, activation of PPARD may improve hepatic steatosis via directly suppressing the expression of cytokines or transcription factors associated with inflammation." (PMID 25887406, 2015).
Hepatic steatosis (continued). "Oleic acid (OA) was shown to induce hepatic steatosis but with normal insulin sensitivity; this was attributable to activation of the G protein-coupled receptor 40 (GPR40)-phospholipase C (PLC)-calcium pathway by OA and upregulation of PPARδ." (PMID 34140896, 2021). "The PPARδ-stimulated hepatic fatty accumulation we observed in our study was accompanied by substantial weight loss, if not preceded, with exceptions of PPARα-KO and PPARδ-KO mice fed GW501516, where neither weight loss nor liver steatosis was observed." (PMID 26604919, 2015). "Our study shows that hepatic steatosis was present in non-tg mice treated with PPARδ agonist; however, it was strictly time-dependent and evident only after 4 weeks of treatment." (PMID 26604919, 2015). "Moreover, dietary genistein had the potential to directly alleviate the inflammatory response by modulating the expression of inflammatory factors such as NF-кB, IL-8, IL-1β, and IFN-γ through the involvement of PPARδ and T-cell factor 3 (TCF3) in laying hens induced fatty liver." (PMID 38540097, 2024).
lung carcinoma (26 papers, 2007 to 2026). "A majority of the studies found that PPARD is overexpressed in lung cancer, with one recent study pointing at the association of high expression levels of this gene with a worse prognosis." (PMID 35342393, 2022). "Peroxisome proliferator-activated receptor-δ, encoded by gene PPARD, is overexpressed in a majority of human lung cancer subtypes, but its role in the tumor progression remains poorly understood." (PMID 35342393, 2022). "Several previous studies suggested a strong association between the expression levels of peroxisome proliferator-activated receptor ß/d- (PPARD-) encoding gene and human lung cancer." (PMID 35342393, 2022). "For PPARD (Peroxisome proliferator-activated receptor-δ) encoding a nuclear transcriptional receptor, there is evidence of its up-regulation in several major human cancers, including colorectal, pancreatic, and lung cancer." (PMID 35053305, 2022). "This suggests that PPARδ activation in the presence of suppressed PG synthesis is critical for the regulation of growth of lung cancer cells." (PMID 35631448, 2022). "Previous studies showed that gene PPARD demonstrated increased expression in patients with lung cancer." (PMID 35342393, 2022). "Our results confirm that PPARD expression is increased in lung cancer, as its elevated levels were detected in all 11 LA datasets and seven out of 9 LSCC cases with log-fold changes 0.37 ± 0.20 and 0.10 ± 0.37 for LA and LSCC, respectively." (PMID 35342393, 2022). "Literature data suggest the involvement of PPARδ in the proliferation of non-small cell lung carcinoma (NSCLC), which is the most common form of lung cancer and the most common cause of death among oncological patients." (PMID 34921177, 2021). "Involvement of PPARδ in lung cancer biology is also undeniable, and the significant differences in expression levels between NSCLC and macroscopically unchanged lung tissue highlight its possible diagnostic role in lung cancer recognition." (PMID 34921177, 2021). "Lung carcinoma was impaired in PPARδ-/- mice, which showed diminished blood flow and an abundance of hyperplastic microvascular structures." (PMID 34712608, 2021). "We observed that CAFs-derived SDF-1 promoted tumour EMT by activation of the CXCR4/β-catenin/PPARδ pathway in lung cancer ADC." (PMID 33637678, 2021). "Similar to CXCR4 and β-catenin, PPARδ inhibitor also blocked the EMT-promoting effect of SDF-1 on lung cancer cells." (PMID 33637678, 2021). "In particular, we investigated the relationship between CAF and activation of the SDF-1/CXCR4/β-catenin/PPARδ signalling pathway within the context of lung cancer ADC." (PMID 33637678, 2021). "Even if some studies unequivocally point at PPARD as a lung cancer-promoting gene, others suggest that ligand-driven activation of PPARD may suppress the growth of lung cancer by inhibiting inflammation." (PMID 35342393, 2022). "The PPARD-driven pathways identified in our study may provide new insights into the understanding of the roles that PPARD plays in lung cancer." (PMID 35342393, 2022). "We confirmed that in most cases of LA and LSCC, the expression of PPARD is increased, while its function may either enhance or suppress the proliferation of lung cancer depending on tissue context." (PMID 35342393, 2022). "In summary, we showed that SDF-1 secreted by CAF might act via the CXCR4/β-catenin/PPARδ signalling pathway to regulate lung cancer EMT." (PMID 33637678, 2021). "Unsurprisingly, there was a line of evidence to support our findings that activating PPARA could reduce metastatic nonsmall cell lung cancer growth and the protective role of PPARD in melanoma metastasis." (PMID 34490113, 2021). "However, the role that PPARD plays in the pathophysiology of lung cancer is far from being clear." (PMID 35342393, 2022). "Thus, targeting the CAF-derived, SDF-1-mediated CXCR4 β-catenin/ PPARδ cascade may serve as an effective targeted approach for lung cancer treatment." (PMID 33637678, 2021).
lung carcinoma (continued). "Analysis of the enriched genes derived from the pathway analysis identified seven genes expressed in both the asthma and lung cancer sets: BCL3, POSTN, PPARD, STAT1, MYC, CD44, and FOSB." (PMID 35406434, 2022). "The fold changes in gene expression in lung cancer relative to asthmatic cell lines were in line with the in silico prediction for the genes BCL3, CD44, PPARD, POSTN, FOSB, and STAT1." (PMID 35406434, 2022). "In particular, the genes BCL3, CD44, PPARD, and STAT1 showed an increase in expression among the mixed group (asthmatics diagnosed with lung cancer) and lung cancer samples." (PMID 35406434, 2022). "In this study, we first explored the expression levels of PPARD in LA and LSCC, which account for about 70% of all lung cancer cases; then, we employed a literature-based pathway analysis to explore the potential role of PPARD in LA/LSCC." (PMID 35342393, 2022). "The other genes, CD44, PPARD, and STAT1, were also observed to be highly upregulated in lung cancer samples compared to asthmatics and healthy controls." (PMID 35406434, 2022). "Analysis of the enriched genes derived from the pathway analysis identified seven genes present in both asthma and lung cancer: BCL3, POSTN, PPARD, STAT1, MYC, CD44, and FOSB." (PMID 35406434, 2022). "The fold change in expression showed significant upregulation for the genes BCL3, CD44, PPARD, POSTN, and STAT1 in lung cancer patients compared to asthmatics." (PMID 35406434, 2022). "Another study showed that the treatment of a lung cancer cell line, A549, with SR13904, a PPARδ antagonist, leads to significantly lower levels of a variety of cell cycle proteins." (PMID 35631448, 2022). "However, the results from this study warrant further investigation into the molecular mechanisms of the four genes (PPARD, STAT1, BCL3, and POSTN) in both asthma and lung cancer cell lines, independently and in combination." (PMID 35406434, 2022). "Expression data analysis showed that PPARD demonstrated increased expression in 18 out of the 20 LA/LSCC independent datasets, which supported the previous finding that PPARD was overexpressed in the majority of lung cancers." (PMID 35342393, 2022). "To facilitate our understanding of the role of the PPARD-encoding gene in lung cancer, we explored its activity of PPARD in expression dataset profiling major subtypes of lung cancer, namely, LA and LSCC, and an influence of the increase in PPARD expression on the pathophysiology of LA and LSCC." (PMID 35342393, 2022). "Our results suggested a mixed role of PPARD in LA/LSCC, which may add new insights into the understanding of the PPARD-lung cancer relationship." (PMID 35342393, 2022). "However, there is a lack of discussion explaining PPARD overexpression in the etiology and development of lung cancer." (PMID 35342393, 2022). "Similarly, BCL3, CD44, PPARD, and STAT1 were upregulated in both the mixed group and lung cancer samples; thus, they may also be involved in the transition." (PMID 35406434, 2022).
melanoma (26 papers, 2008 to 2025). A malignant, usually aggressive tumor composed of atypical, neoplastic melanocytes. "From studies of melanoma cells, 1,25D3 treatment increased the expression of PPARα and PPARδ, and treatment with PPARα and PPARδ ligands increased VDR expression." (PMID 39273194, 2024). "In melanoma, study has shown that PPARδ activation modulated the migration and invasion of melanoma cells by up-regulating Snail expression." (PMID 35151320, 2022). "Several studies demonstrate that activation of PPARδ increases proliferation and tumorigenesis of melanoma, liver, intestinal adenoma, and prostate cancer cell lines." (PMID 29212212, 2017). "We therefore determined whether agonist anti-CD40 mAb (FGK45.5 or FGK) in combination with PPARγ (T0070907 or T007) or PPARδ (GSK3787 or GSK) inhibitor may achieve efficient antitumor responses in mice with established B16 melanoma (left)." (PMID 37291146, 2023). "Although PPARδ is expressed in melanocytes, its role in this cell type has never been investigated, which seems a missed opportunity since ligand-mediated PPARδ activation might protect against melanoma." (PMID 34298981, 2021). "Accordingly, it is possible that PPARδ may also inhibit TSP-1 in other types of cancer, particularly melanoma; further studies are needed to clarify the exact role of PPARδ in expression of TSP-1." (PMID 29212212, 2017). "Analysis of the TCGA-SKCM and GTEx datasets revealed elevated expression of NF2, SUZ39H1, CDC25A, GLRX5, and CISD3 in melanoma tissues, in contrast with the reduced expression of VDR, PPARD, CAMKK2, NT5DC2, and CHP1A." (PMID 40860143, 2025). "On the other hand, some studies indicate that pharmacologic activation of PPARδ by its agonists (GW0742 and GW501516) inhibited proliferation of the murine melanoma cells, accompanied by downregulation of WT1." (PMID 28458685, 2017).